POLG (DNA polymerase gamma, catalytic subunit)
Diseases named in the same sentence as POLG in open-access papers (continued):
Sharing a sentence is not in itself a finding about the gene and the disease.
Friedreich ataxia (10 papers, 2013 to 2025). An inherited condition that affects the nervous system and causes movement problems. "Diseases such as Friedreich’s ataxia and MIRAS (caused by POLG mutations) present an extended phenotype, maybe derived from the equal vulnerability that these variants confer to the mitochondria in the whole organism." (PMID 31110700, 2019). "Despite the known role of mitochondria dysfunction in cerebellar degeneration that usually leads to ataxia, it is not clear why diseases such as POLG and Friedreich’s ataxia occur with many systemic clinical manifestations." (PMID 31110700, 2019).
Leigh syndrome (10 papers, 2015 to 2025). "In patients with Leigh syndrome due to mutations others than SURF1 and POLG, hypertrophic olivary degeneration is hardly found with the exception of one case of PDH deficiency." (PMID 25887401, 2015). "Likewise, although human patients with mutations in the exonuclease “proofreading” domain of POLG have been linked to diseases such as Alpers and Leigh syndrome, PolgD257A mutator mice do not mirror a specific model of mitochondrial disease." (PMID 39969190, 2025). "However, in this article we present cranial nerve enhancement in Leigh syndrome, confirming that it is not a unique feature of POLG-related disorders." (PMID 39066889, 2024).
ophthalmoplegia (10 papers, 2015 to 2025). Weakness or paralysis of at least one of the muscles controlling the movement of the eye. "The proband did not present with ophthalmoplegia, and whether her HL is caused by this POLG variant remains unclear." (PMID 40725402, 2025).
diabetes (8 papers, 2010 to 2025). "A higher proportion (11%) of patients with mutations in POLG had diabetes, but unlike MIDD, these patients invariably have severe complex, multisystem disease of which diabetes is a coexisting rather than presenting feature." (PMID 35552684, 2022).
Dysarthria (8 papers, 2013 to 2025). Dysarthric speech is a general description referring to a neurological speech disorder characterized by poor articulation. "Sensory ataxic neuropathy, dysarthria, and ophthalmoparesis (SANDO) syndrome is a rare manifestation, often associated with POLG mutations." (PMID 41220167, 2025). "Sensory ataxic neuropathy with dysarthria and ophthalmoparesis (SANDO) is a rare phenotype resulting from pathogenic variants of mitochondrial DNA polymerase gamma (POLG)." (PMID 29644085, 2018). "The target of ‘Nabumetone’ is ‘Prostaglandin G/H synthase 2’ (PTGS2), the disease gene of ‘Sensory Ataxic Neuropathy, Dysarthria, And Ophthalmoparesis; Sando’ is ‘DNA polymerase subunit gamma-1’ (POLG)." (PMID 24244318, 2013). "However, innumerable mutations throughout the POLG gene—even a few heterozygous—cause a variety of phenotypes, including PEO-plus, sensory ataxic neuropathy, dysarthria, and ophthalmoparesis (SANDO), mitochondrial recessive ataxia syndrome (MIRAS), and PD, all reviewed by Dr. William Copeland." (PMID 31718067, 2019).
mitochondrial neurogastrointestinal encephalomyopathy (8 papers, 2008 to 2025). A syndrome characterized by the association of gastrointestinal dysmotility, peripheral neuropathy, chronic progressive external ophthalmoplegia and leukoencephalopathy. "Mutations in the gene coding for the catalytic subunit of mtDNA polymerase (POLG) are associated with a range of syndromes characterized by secondary mtDNA defects, including mtDNA depletion and multiple deletions (Mitochondrial DNA depletion syndrome 4B, MNGIE type; OMIM # 613662)." (PMID 36551277, 2022). "Many of these disorders are only known to affect children, but two disorders of mtDNA maintenance can present with prominent leukoencephalopathy in adulthood, namely mitochondrial neurogastrointestinal encephalomyopathy (MNGIE) and POLG mutations." (PMID 30467211, 2019).
Mitochondrial myopathy (7 papers, 2019 to 2024). "Since the first publication of POLG mutations leading to mitochondrial myopathies, over hundred different POLG mutations have been identified with a wide range of phenotypical presentations." (PMID 31991853, 2020). "POLG mutations are well-known as a frequent cause of mitochondrial myopathies of nuclear origin." (PMID 31991853, 2020). "Mutations in POLG (one case), TSEN54 (one case), TMEM70 (one case), and KARS (one case) were eventually identified only after the biochemical data, as the histopathology study did not clearly indicate a mitochondrial myopathy." (PMID 34675869, 2021).
progeria (7 papers, 2011 to 2024). "Other murine models of progeria (e.g. Lamin A- and Zmpste24-deficient, Wrn−/−, Terc−/−, PolgAmut/mut, Klotho−/−, PolG and XPD strains) also do show osteoporosis." (PMID 31553309, 2019). "The POLG-based mutator systems, which display a striking progeroid syndrome in mice, have emerged as the predominant model for obtaining high levels of stochastic mtDNA mutations." (PMID 31337756, 2019). "Both mouse models showed similar progeria-like phenotypes and shared the same D257A mutation on the second exonuclease domain of PolgA (the mouse homolog of POLG) that caused a profound reduction of the exonuclease activity but no decrease in DNA polymerase activity." (PMID 22125488, 2011). "PolG mice showed multiple features of progeria, including kyphosis and greying of fur, and became too frail to survive instrumentation beyond 32 wk; we therefore examined vascular aging markers between 8 and 32 wk of age in both WT and PolG mice." (PMID 29745022, 2018). "PolG knocking mice (PolG mut/mut) were used as a model of progeria." (PMID 39125960, 2024). "We utilized the heterozygous PolG mutator mouse (PolG+/mut) because it accumulates mtDNA point mutations ~ 500‐fold > wild‐type mice (WT), but fails to develop an overt progeria phenotype, unlike PolGmut/mut animals." (PMID 33049094, 2020).
ptosis (7 papers, 2010 to 2025). The drooping of the upper eyelid. "PEO, ptosis and proximal muscle weakness are well recognized as the predominant clinical features seen in adult patients with POLG and PEO1 (C10ORF2; Twinkle) mutations." (PMID 23107649, 2012). "We describe a patient with myopathy, PEO, and ptosis associated with biallelic POLG mutations." (PMID 32042919, 2020). "Dominant POLG variants often manifest as adult-onset slowly progressive disease, usually PEO, ptosis, and myopathy, although other features may manifest later in life." (PMID 38804971, 2024).
sarcopenia (7 papers, 2013 to 2025). Progressive decline in muscle mass due to aging which results in decreased functional capacity of muscles. "For example, exercise ameliorates the premature aging-related outcomes of the POLG mutator phenotype on sarcopenia, cardiomyopathy, brain atrophy, fat deposition and hemoglobin production." (PMID 29875308, 2018). "MtDNA mutator mice (PolG) begin to display muscle wasting as early as 8 months of age and therefore animals were divided into two groups, young (3–6 months) and older (8–15 months), the latter representing the animals with higher mtDNA mutation rates and premature sarcopenia." (PMID 23935986, 2013). "However, the responses observed in muscle from PolG mice differed from that of normally-aged muscle implying that the signals causing sarcopenia are not homogenous and provide support for a multifactorial etiology of muscle wasting." (PMID 23935986, 2013).
bipolar disorder (6 papers, 2015 to 2023). A disorder of the brain that causes unusual shifts in mood, energy, activity levels and the ability to carry out day-to-day tasks. "Clinical studies showed that around 20% of patients with mitochondrial disease have comorbid bipolar disorder, whereas 0.38% of patients with bipolar disorder had mutations of POLG (polymerase γ) causative for mitochondrial disease." (PMID 29892051, 2018). "POLG downregulation in bipolar disorder has previously been demonstrated in lymphoblastoid cells;8 however, we believe our study is the first to demonstrate POLG downregulation in PBMCs of bipolar disorder patients." (PMID 26241352, 2015). "We found downregulation of POLG and OGG1 expression in bipolar disorder patients compared with healthy control subjects." (PMID 26241352, 2015). "We found downregulation of two genes, POLG and OGG1, in bipolar disorder patients compared with healthy control subjects after correction for multiple testing and adjusting for possible confounders." (PMID 26241352, 2015). "The present findings of altered POLG, OGG1 and NDUFV2 expression point to disturbances within mitochondrial function and DNA repair mechanisms in bipolar disorder." (PMID 26241352, 2015). "After Bonferroni correction, POLG (P=0.001) and OGG1 (P=0.001) remained significantly downregulated in bipolar disorder patients." (PMID 26241352, 2015). "The effect of medication on OGG1 and POLG expression in bipolar disorder patients in vivo has not previously been investigated." (PMID 26241352, 2015). "In addition, we demonstrated aberrant regulation of the POLG, NDUFV2 and, for the first time, the OGG1 gene, pointing to disturbances within mitochondrial function and DNA damage repair mechanisms as pathophysiological mechanisms in bipolar disorder." (PMID 26241352, 2015).
depression (6 papers, 2018 to 2024). "Moreover, genotype T/A of POLG c.-1370T > A (rs1054875) significantly increased the incidence of cured depression." (PMID 37834200, 2023). "According to the best of our knowledge, this paper is the first to report that SNPs located in genes encoding proteins maintaining mitochondrial genome integrity, i.e., EXOG, POLG and ENDOG, affect the incidence, onset, severity and treatment of depression." (PMID 37834200, 2023).
liver disease (6 papers, 2016 to 2024). "This contrasts with the experience in ALF due to hepatocerebral MDS from bi-allelic mutations in POLG, DGUOK or MPV17 commonly manifesting as multi-system disorders before or shortly after onset of liver disease." (PMID 27483465, 2016). "One child who was homozygous for a p.(Leu304Arg) mutation in POLG presented at 18 months old, recovered with supportive treatment only and remains well without evidence of liver disease 6 years later." (PMID 27482763, 2016).
sensory ataxia (6 papers, 2016 to 2025). Any ataxia in which the causes of the disease is a perturbation of the sensory system, leading to its dysfunction. "20-year-old girl with identification of POLG variants [c.2243G>C (p.W784S)]; [c.3609_3612dupAACT] showed progressive sensory ataxia, intractable generalized epilepsy, magnetic resonance imaging (MRI)-confirmed cerebellum atrophy, and speech delays." (PMID 32999401, 2020). "Sensory ataxia due to dorsal root ganglionopathy is one of the defining features in SANDO phenotype (sensory ataxia, neuropathy, dysarthria and ophthalmoplegia) caused by POLG mutations." (PMID 26315846, 2016).
status epilepticus (6 papers, 2013 to 2025). Status epilepticus is defined as a continuous seizure lasting more than 30 min, or two or more seizures without full recovery of consciousness between any of them. "The neurological symptoms and lesions can spontaneously reverse, but especially patients with mitochondrial disease related to pathogenic variants in the nuclear gene POLG are at higher risk of death from status epilepticus." (PMID 39666093, 2024). "Seizures and status epilepticus are common manifestations of POLG variants." (PMID 40062103, 2025). "The treatment of mitochondrial epilepsy associated with POLG variants is particularly challenging as super-refractory status epilepticus is not uncommon." (PMID 39666093, 2024). "We found POLG p.A467T mutation in trans with p.R417T associated with intractable epilepsy with status epilepticus as the first manifestation of the disease without any liver symptoms leading to severe epileptic encephalopathy and death at the age of 2.5 years." (PMID 23448099, 2013).
autosomal dominant progressive external ophthalmoplegia (5 papers, 2020 to 2024). Autosomal dominant form of progressive external ophthalmoplegia. "The POLG-related disorders comprise a continuum of overlapping phenotypes based on biallelic POLG pathogenic variants except autosomal dominant progressive external ophthalmoplegia (adPEO,MIM #157640)." (PMID 39415983, 2024). "In a groundbreaking 2001 paper, the heterozygous POLG c.2864A>G/p.Y955C mutation (hereafter POLG Y955C) cosegregated with autosomal dominant progressive external ophthalmoplegia (adPEO) in a family, establishing that a POLG mutation causes the disorder." (PMID 35760101, 2022).
breast carcinoma (5 papers, 2012 to 2024). "Despite this, in our previous study, we found that POLG rs2072267 was significantly associated with disease progression in breast cancer patients." (PMID 33922707, 2021). "This study is the first to investigate the role of CAG repeat polymorphisms in the nuclear POLG gene, which encodes mitochondrial DNA polymerase-gamma, in breast cancer risk." (PMID 22276120, 2012). "In contrast, our study evaluated germline polymorphisms in POLG in both breast cancer cases and in controls." (PMID 22276120, 2012). "Furthermore, the model trained with human breast cancer cell data successfully predicted the differences in metabolic phenotypes of macrophages from control and POLG-mutated mice." (PMID 38420625, 2024). "Our previous research suggests that mutations in the POLG gene may result in depletion of mtDNA and confer breast cancer phenotype." (PMID 22276120, 2012). "Taken together, our results indicate that STAT3 mediates PRRG4-induced POLG expression in breast cancer cells." (PMID 38102641, 2023). "Our study uncovers that PRRG4 via Src-STAT3 regulates POLG expression by increasing the transcription of POLG in breast cancer cells." (PMID 38102641, 2023). "This pilot study suggests the possibility of an association between altered POLG-CAG repeat-length and an increased risk of breast cancer in AA women." (PMID 22276120, 2012). "Since STAT3 is a transcription factor, we hypothesized that STAT3 promotes POLG transcription in breast cancer cells." (PMID 38102641, 2023). "Subsequently, we wanted to examine whether POLG is involved in PRRG4’s action in enhancing breast cancer cell migration and invasion." (PMID 38102641, 2023). "Moreover, PRRG4 elevated migratory behaviors and mitochondrial function of breast cancer cells through POLG." (PMID 38102641, 2023). "However, the significance of the CAG repeat polymorphism of POLG in breast cancer has not been investigated." (PMID 22276120, 2012). "In a recent study of the POLG gene, we reported the CAG repeat expansion occurs in 20% of breast cancer patients." (PMID 22276120, 2012). "As mitochondrial DNA polymerase gamma (POLG) is essential for mtDNA replication, we hypothesized that PRRG4 may regulate mtDNA content by controlling POLG expression through STAT3 in breast cancer cells." (PMID 38102641, 2023). "Furthermore, results from transwell assay also revealed that POLG overexpression enhanced cell migration and invasion, and rescued the reduced cell migration and invasion induced by PRRG4 knockdown in breast cancer cells." (PMID 38102641, 2023). "Other epidemiologic studies have shown either a positive or negative correlation of CAG repeats with sporadic breast cancer, and one study reported an inverse correlation between POLG-CAG repeat length (r = −0.81) and the age of onset of disease in Friedreich's Ataxia (FRDA) patients." (PMID 22276120, 2012).
cardiomyopathy (5 papers, 2018 to 2025). A disease of the heart muscle or myocardium proper. "Nuclear gene defects in mtDNA maintenance, such as mutations in TK2 and POLG, can result in mtDNA depletion or multiple deletions, undermining respiratory chain integrity and precipitating severe early-onset cardiomyopathy." (PMID 41301490, 2025). "Furthermore, we hypothesize that cardiomyopathy observed in the patient may be partially explained by the presence of the additional heterozygous likely pathogenic variant: c.2243G > C (p.Trp748Ser) in the POLG gene, while cardiac abnormalities are rather uncommon for LGMDR1." (PMID 38758368, 2024).
lactic acidosis (5 papers, 2014 to 2025). Metabolic acidosis characterized by the accumulation of lactate in the body. "While the details of this cascade have not been fully characterized, the report of a novel, functional mtDNA POLG mutation being associated with NRTI-associated lactic acidosis lends weight to the POLG inhibition hypothesis." (PMID 41480619, 2025).
liver dysfunction (5 papers, 2016 to 2022). "Different mutations in the POLG gene result in a wide variety of clinical phenotypes such as seizures, neurodegenerative disorders, and liver dysfunction." (PMID 36672794, 2022). "POLG mutations result in disorders that span a continuum of phenotypes, including liver dysfunction and failure." (PMID 34652935, 2021). "Most of the valproate induced hepatopathy subjects reported in the literature were carriers of pathogenic mutations in POLG." (PMID 29783990, 2018).
male infertility (5 papers, 2014 to 2025). The inability of the male to effect fertilization of an ovum after a specified period of unprotected intercourse. "Another gene that encodes DNA polymerase gamma (POLG), an enzyme responsible for the replication and repair of mitochondrial DNA, is also associated with sperm dysfunction; however, the role of POLG in male infertility remains controversial." (PMID 35626747, 2022). "Several human genes are known with mutations causing male infertility (AR; AZF gene families; CFTR, DM-1, DNAH gene family, FGFR1, FSHR, INSL3, KAL-1, LGR8-GREAT, LHR, POLG)." (PMID 26097523, 2015).
Mitochondrial encephalopathy (5 papers, 2021 to 2024). "Our data showed that patients with pathogenic POLG variations showed the characteristics of mitochondrial encephalopathy, with refractory epilepsy, progressive liver function impairment, as the main clinical symptoms, acute liver failure occured after valproic acid application." (PMID 34690748, 2021). "Another patient P3 harbored variants in two genes namely POLG (p.Arg1187Trp) and SUCLG2 (p.Glu79*) reported to be associated with mitochondrial respiratory chain diseases and mtDNA depletion, impaired respiratory complex subunits and mitochondrial encephalopathy, respectively." (PMID 33484326, 2021).
polyneuropathy (5 papers, 2013 to 2025). A disease or disorder affecting more than one nerve. "Lastly, mitochondrial point mutations and single mitochondrial DNA deletions very rarely cause CPEO associated with polyneuropathy and neuropathic pain, and POLG-related disease should be considered in this scenario, instead." (PMID 35350396, 2022). "In addition to epilepsy, he had shown phenotypic polyneuropathy from the age of 13, which is why a genetic investigation was initiated involving his parents and sisters, in which the variants c.695G>A in exon 3 and c.2209G>C in exon 13 of the POLG gene were detected in all three siblings." (PMID 40062103, 2025). "However, a patient carrying two heterozygous POLG variants in different exons, phenotypically manifesting initially as polyneuropathy and later with an SLE and seizures, has not yet been described." (PMID 40062103, 2025).